KIT (KIT proto-oncogene, receptor tyrosine kinase)
Diseases named in the same sentence as KIT in open-access papers (continued):
Sharing a sentence is not in itself a finding about the gene and the disease.
melanoma (continued). "The results of this study showed that the PI3K-Akt signaling pathway and the key genes CDK2, CDK4, KIT, and VWF promoted the proliferation and metastasis of melanoma, and they were significantly related to the prognosis of patients with melanoma." (PMID 34582363, 2021). "PAX3, a transcription factor involved in melanocyte development, the receptor tyrosine kinase KIT, CDKN1C, and EPHA5 were upregulated in the melanoma compared to the atypical nevus, while NTRK3 and ROS1 were downregulated in the same comparison." (PMID 35052351, 2021). "KIT, PDGFRA, KDR, CDK4 and CCND1, MDM2, and TERT amplifications were frequently observed in Triple-WT melanomas." (PMID 34804979, 2021). "In this article, various melanoma biomarkers including BRAF, MEK, RAS, c-KIT, VEGFR, c-MET and PI3K are described, and their potential mechanisms for drug resistance are discussed." (PMID 33807778, 2021). "Identifying which human melanoma subtypes (e.g., BRAF, NRAS, c-KIT, etc) in which an interface cell state is found awaits larger datasets of freshly isolated tumors subjected to scRNA-seq and/or SRT." (PMID 34725363, 2021). "NRAS, KIT, EGFR, MET, RAB27A, and other pro-progression proteins have all been found within exosomes released by melanomas." (PMID 35008286, 2021). "In humans, the use of tyrosine kinase inhibitors (TKIs) has a better effect on patients affected by tumors bearing SNPs in KIT, particularly in GIST, some types of melanomas, chronic myeloid leukemia, and systemic mastocytosis." (PMID 33321993, 2020). "This was observed in human cultured melanoma cells and in cutaneous melanomas (from radial growth phase to vertical growth phase and metastatic melanoma), which led to the hypothesis that the loss of KIT could represent a negative prognostic factor." (PMID 33321993, 2020). "Using three melanoma cell lines which are dependent on oncogenic KIT, we showed that FGF2 drastically reduced the effect of the different KIT inhibitors pointing to an important role of the FGF2/FGFR axis in the resistance to KIT inhibitors." (PMID 32344828, 2020). "All eligible gene sets were analyzed, and the 8 genes (GPR87, KIT, SH3GL3, PVRL1, ATP1B1, CDAN1, FAU, and TNFSF14) with the greatest prognostic impact on melanoma." (PMID 32411243, 2020). "In addition, a broad predictive analysis allows identification of genomic aberrations that are rarely considered by clinicians, e.g. MSI in a non-MSI-prone tumor or a KIT mutation in melanoma, which might be beneficial for treatment options." (PMID 32264863, 2020). "The spectrum of genomic alterations in melanoma involve multiple genes and signaling networks, but the most frequently altered pathways are MAPK, PIK3CA, KIT signaling, and apoptosis/cell senescence pathways." (PMID 32850962, 2020). "We identified an 8-gene signature (i.e., GPR87, KIT, SH3GL3, PVRL1, ATP1B1, CDAN1, FAU, and TNFSF14) with independent prognostic value on melanoma." (PMID 32411243, 2020). "In particular, we focused on KIT, BRAF, and BCL-2, three relevant target genes in melanoma known to bear G4-forming sequences within their promoters." (PMID 31635389, 2019). "Melanomas which are wild type for BRAF, NRAS, and NF1 show amplifications of KIT, platelet-derived growth factor receptor α (PDGFRA), and vascular endothelial growth factor receptor 2 (VEGFR2) in 10–20% of cases." (PMID 30987166, 2019). "Second, we expanded our cell line panel and included BRAF, and ‘wild type’ melanoma cells including GNAQ and c-KIT mutants." (PMID 30405888, 2018).
melanoma (continued). "Within the input layer, representative examples for melanoma are the receptor tyrosine kinases (RTK), c-KIT, and anaplastic lymphoma kinase (ALK)." (PMID 29946532, 2018). "The scenario of genetic alterations contributing to melanoma gene signature was completed by somatic CNVs, such as gene amplifications in CCND1, CDK4, KIT, MITF, and TERT as well as gene deletions in CDKN2A and PTEN." (PMID 30218391, 2018). "Hence, the information about the presence or absence of a certain mutation in BRAF or NRAS or KIT is not sufficient to predict whether or not a melanoma cell will enter the brain." (PMID 30053879, 2018). "From this, we identified a panel of 6 genes, ALDH1A1, HSP90AB1, KIT, KRT16, SPRR3 and TMEM45B whose expression values discriminated metastatic from primary melanoma (87% classification accuracy)." (PMID 29229936, 2017). "For example, if testing for melanoma is done using a combination of three single gene tests for BRAF, NRAS, and KIT, this costs less than the panel." (PMID 28196074, 2017). "In order to compare NGS with conventional molecular testing under routine laboratory conditions, we calculated the turn-around time and costs for three commonly melanoma-related genes (BRAF, NRAS, KIT) in eight samples." (PMID 28356599, 2017). "In the old situation within specialised hospitals, we assumed that multiple single-gene tests were performed, minimally three for NSCLC patients (a multigene panel, HER2/EGFR, and ALK, ROS, RET, or MET) and two for melanoma patients (BRAF and NRAS or KIT)." (PMID 27899957, 2016). "There are multiple reports of the particular KIT V559A substitution detected in our patient, some in familial GIST as well as for melanomas." (PMID 26102504, 2015). "All in all, melanoma cells display a unique composition of cytokine receptors and differ from normal melanocytes in expression of EPO-R, ErbB4, and KIT." (PMID 24489649, 2014). "It has been previously reported that Bim was also critical for apoptosis following KIT inhibition by imatinib in GIST, BRAF V600E inhibition by imatinib in melanoma and EGFR inhibition by gefitinib in non-small cell lung cancers." (PMID 25431951, 2014). "Next, we searched for CNAs in genes known to be affected by CNAs in melanoma (BRAF, KIT, MITF, CCND1, CDK4, PTEN, CDKN2A and AKT3)." (PMID 24399611, 2014). "A well-studied cluster on chromosome 4q containing PDGFRA, KIT, and KDR was amplified in glioma and melanomas." (PMID 24874471, 2014). "A typical example of a genomic panel recommended for cancer diagnosis is a panel comprising of BRAF, KIT, NRAS, GNA11 and GNAQ for Melanomas." (PMID 23863689, 2013). "Abnormalities in TFAP2A, KIT, and MITF expression in melanoma highlight the importance of this pathway in human disease." (PMID 20862309, 2010). "Since AP-2α regulates several genes associated with the metastatic potential of melanoma including c-KIT, VEGF, PAR-1, MCAM/MUC18, and p21Waf1, our data identified CREB as a major regulator of the malignant melanoma phenotype." (PMID 20805990, 2010). "To further elucidate the role of c-KIT and BRAF in mucosal melanoma, we analysed these two targets in 39 patients with mucosal melanomas treated in our Department." (PMID 19018266, 2008). "By contrast, mucosal and other non-cutaneous melanomas have lower rates of BRAF and NRAS mutations and higher frequencies of KIT and other alterations." (PMID 41384184, 2025). "The efficacy of approved small-molecule inhibitors in melanoma is primarily determined by the presence of actionable mutations—most notably BRAF V600 and activating KIT alterations—rather than by the tumor’s anatomical site alone." (PMID 41302945, 2025).
melanoma (continued). "SSM: Superficial spreading melanoma; NM: Nodular melanoma; LMM: Lentigo maligna melanoma; ALM: Acral lentiginous melanoma, DM: Desmoplastic melanoma; BRAF: B-Raf proto-oncogene, serine/threonine kinase; KIT: KIT proto-oncogene receptor tyrosine kinase." (PMID 40984902, 2025). "The remaining melanomas can be described as triple-negative (triple-wild-type: BRAF, RAS, KIT)." (PMID 40361349, 2025). "KIT mutations are most frequently observed in acral, mucosal, and chronically sun-damaged (CSD) melanomas and are rarely found in non-CSD cutaneous melanoma." (PMID 41301010, 2025). "Notably, four clinical trials on myeloma, diffuse large B cell lymphoma (DLBCL), melanoma, and NSCLC are ongoing which combine anti-PD1 antibody and IL-17A (NCT03111992), CD22 (NCT03287817), KIT (NCT04493203), or AXL (NCT04681131), respectively." (PMID 38349411, 2024). "The presence or location of mutations in KIT is not used as a diagnostic biomarker for canine MCT, GIST, or melanoma, with the gold standard being histopathological diagnosis." (PMID 38787171, 2024). "In contrast, the OFA, but not OST, includes KIT gene, a key player in the pathogenesis of melanoma, especially in acral and mucosal melanoma with a frequency of 1–7%." (PMID 39000050, 2024). "These tumors are usually negative for KIT; the finding is useful for differential diagnosis, although pathologists should pay attention to the fact that neuroendocrine tumor and malignant melanoma can express the KIT protein." (PMID 38609732, 2024). "Yet, in a multicenter, phase II trial of 17 c-KIT-mutant or -amplified mucosal melanoma patients, Hodi and colleagues reported an ORR of 64% with imatinib among those with c-KIT mutations but not amplification." (PMID 39001457, 2024). "For instance, genomic analyses have established the molecular classification of melanoma based on the most frequent driver oncogenes (BRAF, NRAS, KIT) and have also revealed a long list of rare events, whose contribution to melanoma progression toward metastasis remain mostly unclear." (PMID 37047539, 2023). "Although KIT mutations were detected in approximately 40% of Japanese patients with AM, KIT inhibitors, such as imatinib and sunitinib, are not approved for treating advanced melanoma in Japan." (PMID 37636577, 2023). "Here we used whole genome sequencing to genetically characterize the triple-wild-type melanoma (TWM), termed here as BRAF, RAS and KIT wild type (the most frequent oncogenic drivers of skin melanoma), using the most common histological forms and excluding rare ones." (PMID 36980598, 2023). "No cytotoxic effect was observed for the primary melanoma cell line WM3211 (VGP), with a wild type for BRAF, PTEN, N-RAS, and CDK4, and mutation at position 576 in the c-KIT gene, even for long incubation times—72 h." (PMID 37097377, 2023). "In accordance with the published data, the three ALM melanomas in our cohort were not BRAF mutated; rather, they carried NRAS, KIT and NF1 mutations." (PMID 36765773, 2023). "On the hand in conventional melanomas, resembling Spitz tumors or not, the initiating event is the involvement of BRAF, NRAS, KIT or NF1 mutations." (PMID 38031947, 2023). "Early trials with imatinib showed high response rates in KIT-mutant, but not KIT-amplified, melanomas." (PMID 35513054, 2022). "Most ALM is included in melanomas not consistently associated with CSD, and the common genetic alterations include KIT mutations." (PMID 35954498, 2022). "Typically, these panels only cover driver mutations in genes known to be involved in melanoma, such as BRAF, NRAS, KRAS, KIT, GNAQ, and GNA11, and do not include genes that have been recently found by WES/WGS studies." (PMID 36431075, 2022).
melanoma (continued). "The loss of MNK1/2 genes did not affect cell proliferation in MEFs and KIT-mutant melanoma cells, but inhibiting the activity of MNK2 in non-small-cell lung cancer impaired the proliferation and migration." (PMID 35877722, 2022). "Previously, ‘driver-negative’ (i.e. the absence of BRAF, NRAS, KIT, GNAQ or GNA11 mutations) melanoma cell-lines that were less sensitive to trametinib and which displayed paradoxical activation of MEK1/2, were found to show basal EGFR activation due to AREG." (PMID 35993275, 2022). "Furthermore, in melanoma cells, up-regulation of the thrombin receptor PAR-1 and the matrix metalloproteinase (MMP)-2, and down regulation of the c-KIT were found to be crucial for the metastatic progression of these cells." (PMID 34439864, 2021). "Melanomas are currently subjected to BRAF and, in some instances, KIT genetic analysis." (PMID 34681592, 2021). "Imatinib mesylate, a small-molecule inhibitor of the KIT tyrosine kinase, provides a rapid but not durable clinical response in KIT-mutant melanoma." (PMID 34889232, 2021). "In a study investigating the prognostic and predictive values of oncogenic BRAF, NRAS, c-KIT, and MITF in melanoma, it was found that initial lymph node involvement was more frequent in patients with BRAF-mutated melanomas, than in cases presenting other mutations." (PMID 34209415, 2021). "In cell lines and mice, siRNA silencing of the gene for this kinase led to cell death in c-KIT-mutated melanomas and GIST tumors, even those with drug resistance, without effecting cells not dependent on c-KIT." (PMID 33807778, 2021). "In the GSE32474 dataset, the expression levels of CDK2, CDK4, KIT, and VWF in the melanoma metastasis group were significantly higher than those in the melanoma primary focus group (t = 2.616, 2.244, 2.137, and 2.570, respectively; logFC = 1.206, 0.240, 1.573, and 0.168, respectively; p < 0.05)." (PMID 34582363, 2021). "Moreover, this location of the melanoma is an entirely distinct entity from skin melanoma and melanomas of the nasal cavity, while cervix melanomas also have some particularities, and do not suffer recurrent KIT mutations, or mutations of the NRAS and SF3B1 genes." (PMID 34209084, 2021). "As imatinib showed remarkable effective clinical responses in several cancers, and as the expression of its targets (c-KIT, PDGFR) has been validated in melanoma, it was also tested in phase II trial but showed limited clinical responses as a single agent, even in tumors with high PTKs expression." (PMID 33918490, 2021). "The highest frequency of KIT mutations was in mucosal melanoma (4/8, 50%), followed by acral (3/36, 8.3%), CSD (3/64, 4.7%) and non-CSD melanomas (11/384, 2.9%)." (PMID 33648909, 2021). "One study found that KIT expression is significantly diminished in melanoma patients with nodal metastases as compared to those without metastasis." (PMID 35008286, 2021). "Based on FISH, we found that the KIT gene is generally close to the nuclear periphery in NTF2 low cells, as opposed to its more central nuclear location in NTF2 high dox + cells and VGP primary melanoma cells." (PMID 34880267, 2021). "Our data showed that the frequency of KIT mutations was low in non-acral melanoma and that, contrary to previously reported, prevalence was not different between CSD and non-CSD melanomas." (PMID 33648909, 2021). "Due to simultaneous reactivation of MAPK function, selective PI3K inhibition did not replicate imatinib activity in c-KIT-mutant melanoma." (PMID 33807778, 2021). "We observed that gynecologic melanoma harbored distinct mutation rates in c-KIT, BRAF, SF3B1, KRAS and NRAS genes compared with non-gynecologic melanoma." (PMID 34102999, 2021). "The genomes of both human cutaneous and mucosal melanomas were deeply studied, and human mucosal melanomas (hMMs) showed a higher frequency of aberrations in the KIT gene rather than their cutaneous counterparts." (PMID 33321993, 2020).
melanoma (continued). "Unlike GISTs, which are characterized by secondary KIT gene mutations, the activation of MAPK and PI3K signaling pathways has been proposed as a possible mechanism of resistance in melanoma." (PMID 32825562, 2020). "Our results suggest that LCH may belong to the group of KIT-mutant tumors, GIST, mastocytosis, AML, and melanoma." (PMID 32372223, 2020). "The serine/threonine kinase BRAFV600E mutation that disrupts the KIT-NRAS-BRAF-MEK-ERK-CDK4/6-RB pathway is almost always present in both CSD and non-CSD melanomas." (PMID 32283832, 2020). "Beads, emulsion, amplification and magnetics (BEAMing) and droplet digital PCR (ddPCR), two PCR-based techniques, have very high sensitivity, but they are limited by the need for a specific gene target and hence used mostly in wild type melanoma for BRAF, NRAS or c-KIT." (PMID 33233603, 2020). "NGS revealed 118 (26%) of 446 melanomas with no mutation, 42% with BRAF mutations, 25% with NRAS mutations, 4.9% with KIT mutations, and 2.0, 2.7 and 2.7% with HRAS, KRAS and PIK3CA mutations, respectively." (PMID 31277584, 2019). "Overall, in contrast to gastrointestinal tumors, c-KIT appears at present not to be a promising target in melanoma." (PMID 30987166, 2019). "In the present study, we showed that 1 was able to bind and stabilize G4 structures in vitro that form within the promoters of human KIT, BRAF, and BCL-2, which are three genes that may be relevant therapeutic targets in melanoma." (PMID 31635389, 2019). "In review of the published literature using the terms conjunctiva, melanoma, BRAF, KIT, pembrolizumab, ipilimumab, interferon and genetics, we found a 2016 study on the efficacy of anti-PD-1 agents in acral and mucosal melanomas supported its use in clinical practice." (PMID 30909967, 2019). "On the other hand, we checked the impact of ERK activation on MITF (melanogenesis associated transcription factor) because MITF is a critical transcription factor for melanocyte and melanoma cell proliferation, whose stability is reduced when phosphorylated by MAPK or KIT." (PMID 31040916, 2019). "Moreover, several molecular abnormalities and signaling pathways described in specific human melanoma subtypes can be found in canine melanoma, including phosphorylated forms of AKT and ERK1/2, alterations of the receptor tyrosinase KIT and PTEN." (PMID 29534457, 2018). "SCF is the ligand for c-KIT and inhibits the growth of KIT-expressing melanoma cells." (PMID 28427434, 2017). "Dog malignant melanomas share numerous immunohistochemistry similarities (KIT, PTEN, and phosphorylated forms of AKT and ERK1/2) with human melanoma subtypes; particularly with mucosal, digital and ungual localizations that usually show high growth and aggressive behavior." (PMID 29056717, 2016). "The BRAF/NRAS wild-type melanomas, i.e. samples negative for mutations in both BRAF and NRAS, more often had genetic alterations in KIT or NF1 (P < 0.001, Fisher's exact test)." (PMID 25909218, 2015). "The detection of KIT hypermethylation in the advanced tumors of this study (mostly stage III melanomas) was not unexpected and had already been described." (PMID 26106605, 2015). "We defined “pan-negative” samples as those melanomas harboring none of the well-known, specific, and recurrent mutations in the genes BRAF, NRAS, KIT, GNAQ, or GNA11, which are commonly mutated in melanoma." (PMID 25537510, 2015). "We did not observe significant difference in KIT methylation levels between acral and nonacral subtypes, but melanomas as a group were hypermethylated compared to melanocytes." (PMID 26106605, 2015). "Among BRAF mutation-negative melanomas, 6 N-RAS mutations (four Q61R, one Q61K, and one Q61L) and 3 KIT mutations (N822K) were found." (PMID 24591764, 2014).